MYC (MYC proto-oncogene, bHLH transcription factor)
Diseases named in the same sentence as MYC in open-access papers (continued):
Sharing a sentence is not in itself a finding about the gene and the disease.
lung carcinoma (continued). "MYC has a key role in regulating lung cancer cell behavior, regulating lung cancer cell growth, resistance, death, and dissemination by regulating kinesins, anti-apoptotic proteins, and metabolism." (PMID 36311939, 2022). "Despite a higher positive correlation (Pearson correlation coefficient R ≈ 0.84), we determined several known lung cancer-associated genes with high RS and low |log2FC|, such as TRIM28, APP, ESR1, MYC, and EGFR." (PMID 36229842, 2022). "PG (18:1/22:6) was found to be increased in MYC-induced T cell acute lymphoblastic leukemia, renal cell carcinoma, hepatocellular carcinoma, and lung carcinoma." (PMID 35045880, 2022). "A recent study showed that KRT6A promotes growth and invasion of lung cancer cells by regulating glucose-6-phosphate dehydrogenase expression through MYC." (PMID 36275729, 2022). "The deregulation of MYC is related to many kinds of cancers, such as lung carcinoma, glioma, colon adenocarcinoma, and breast adenocarcinoma." (PMID 36057607, 2022). "This cooperation between MYC inactivation and immune checkpoint blockade can effectively reverse immune escape and treat lung cancer." (PMID 34687270, 2022). "The network analysis in LUSC identified key TFs including KLF5 and MYC in basal cells, consistent with its amplification and overexpression in lung cancer patients, acting as the prognostic markers of early-stage tumors." (PMID 35027529, 2022). "MYC stained high in 10% of the cases using IHC data from the Human Protein Atlas and its high expression was an unfavorable marker in lung cancer (p = 0.0049, Log-rank)." (PMID 36142846, 2022). "In H460 lung cancer cells, the evaluation of UA compounds’ influence on MYC and KRAS gene expression gave different results than in colon cells." (PMID 35328482, 2022). "Our recent study provided an example of this, showing that LCAT3 recruits FUBP1 to the FUSE region of the MYC promoter, thereby activating MYC transcription to promote lung cancer cell growth and metastasis." (PMID 36257938, 2022). "Among the known driver CNVs found in lung cancer sample, the copy number of MYC and FGFR1 increased in the resistant time point." (PMID 35402275, 2022). "Next, we used MYC as an example to show the integrated gradient attributions for an individual gene in the A549 lung cancer cell line." (PMID 35891778, 2022). "The genomic alteration/mutation analysis of 11 hub-DEGs revealed that the EGFR, MYC, and CHEK1 genes had 12%, 8%, and 1.3% genomic alteration/mutation over the four lung cancer studies." (PMID 35632527, 2022). "In lung cancer, DDX55-associated genes were found to be enriched in proto-oncogene (MYC) targets, and MYC transcription can be regulated by cytokines." (PMID 35847896, 2022). "Dysregulation of MYC occurs in 30–40% of human cancers, including both solid tumors and hematological malignancies, such as breast, colon, lung cancer, melanoma and myeloid leukemias." (PMID 33572152, 2021). "To gain first insights into the working mechanism of KJ-Pyr-9-induced survival decrease in MYC expressing lung cancer cells, we tested for alterations in mRNA levels of several known MYC target genes, such as CCND1, CCND3, and MYC itself." (PMID 33925297, 2021). "As a member of the transcription factor MYC gene family, c-Myc plays a critical role in the development of human tumors, and its overexpression has been detected in lung cancers of different histologic subtypes." (PMID 33849634, 2021). "Restoration of SMARCA1 in vivo significantly reduced lung cancer invasiveness and c-MYC expression, suggesting that inactivated SMARCA1 keeps cancer cells in an undifferentiated state and prevents its response to developmental and environmental stimuli." (PMID 33968920, 2021). "This RNA suppresses the expression of a number of proto-oncogenes, including MYC, and its constitutive expression leads to a decrease in the proliferation and ability of lung cancer cells to invade." (PMID 34440124, 2021).
lung carcinoma (continued). "Two circRNAs were upregulated in lung cancer tissues and cell lines, with oncogenic roles that positively regulated MYC expression." (PMID 34295810, 2021). "In a mouse model of lung cancer, systemic inhibition of the MYC gene using a dominant negative MYC mutant resulted in complete eradication of the lung cancers." (PMID 34761120, 2021). "Hsa_circRNA_103809 promoted lung cancer cell proliferation and invasion by promoting ZNF121 expression via miR-4302 sponging, and thus elevated ZNF121 expression levels, subsequently increasing MYC levels in lung cancer." (PMID 34295810, 2021). "Inhibition of FGFR3 in a urothelial cancer cell line or FGFR1 in a lung cancer cell line resulted in decreased c-MYC protein level." (PMID 34830951, 2021). "LINC01123 lncRNA in lung cancer cells forms a positive LINC01123/miR-199a-5p/MYC regulatory loop with c-Myc factor." (PMID 34440124, 2021). "USP36 and USP37 have been reported to regulate tumorigenesis by preventing MYC degradation in breast and lung cancer [16,35,]." (PMID 34272356, 2021). "Experiments on lung cancer cell lines have shown that the addition of P5C and increased expression of MYC through up-regulation of the enzymes P5CS, PYCR1, PYCR2, PYCRL increases glycolysis." (PMID 34769188, 2021). "We studied the differential response to SAHA in lung cancer cells with oncogenic activation of MYC (hereafter referred to as MYCamp) with respect to those with genetic inactivation of SMARCA4 (hereafter, SMARCA4def)." (PMID 34262032, 2021). "In an experiment on lung cancer cells (with high MYC expression), the effects of MYC knockdown and the enzymes under the control of MYC, PYCR1/2/L, and P5CS, were investigated." (PMID 34769188, 2021). "Taken together, these results indicate that the changes we observed in mouse models, including the upregulation of MYC and ncPRC1.6 targets upon MGA loss, are consistent with those observed in patient data and human lung cancer lines." (PMID 34236315, 2021). "To further investigate the antitumor effects of MYC and HIF1α inhibition in vivo, we first explored xenograft model using H1944 cells which were originally from a non–small cell lung cancer patient." (PMID 33572152, 2021). "Our finding that MYC expression requires continued signaling from RET opens a potentially new avenue for the combinatorial targeting of RET-fusion-driven lung cancers, with RET and new MYC inhibitors to improve response rates." (PMID 33318047, 2020). "In conclusion, we demonstrated that dPCR is an accurate and reliable method for the assessment of the MYC status in tissues, showing that MYC amplification is a common event in lung cancer patients." (PMID 33014186, 2020). "Systemic inhibition of MYC by OmoMYC in KRAS-driven lung cancer, in MYC-induced papillomatosis and in glioma was also shown to have a profound therapeutic effects, and yet only elicited mild and rapidly reversible side effects on normal tissues." (PMID 31636382, 2020). "It was suggested that lung cancer is marked by increased MYC copy numbers showing more aggressive phenotypes." (PMID 33014186, 2020). "For the assessment of MYC alteration in lung cancer, MYC copy numbers were determined in tumor and adjacent nontumor tissue of 129 lung cancer patients using dPCR." (PMID 33014186, 2020). "Immunohistochemically assessed cell positivity for ALDH1A1, SOX2, NANOG, OCT-4, and c-MYC, which are considered as lung cancer stem-like cells markers." (PMID 32500024, 2020). "In this study, we detected an increase of MYC copy numbers in 43% of the analyzed lung cancer samples." (PMID 33014186, 2020).
lung carcinoma (continued). "Although these mechanisms were never explored in sarcoma, other cancer models showed different impacts of aurora kinases inhibitors depending on the expression level of certain genes such MYC in lung cancer." (PMID 32138169, 2020). "c‐MYC stimulates the expression of target genes that play important roles in cell proliferation, growth arrest and apoptosis in lung cancer cells." (PMID 32175651, 2020). "Enhanced expression of different MYC paralogs induces tumors with different biological characteristics in medulloblastoma, prostate cancer, and lung cancer." (PMID 33614505, 2020). "It has been reported that hsa-miR-342-3p regulates BRCA1 expression and MYC transcriptional activity by directly repressing E2F1 in human lung cancers." (PMID 32182819, 2020). "Increasing evidence suggests that microRNAs are involved in EGFR-mediated signaling pathways in lung cancers, including miR-145, which is downregulated and associated with TKI resistance targeting ERK, AKT, Oct4, c-MYC, EGFR, and NUDT1." (PMID 31619200, 2019). "For example, a commonly deregulated pathway in lung cancer is the extension of functions of MYC by translocations and amplifications." (PMID 30634602, 2019). "Taken together, these results suggest that CPA4 enhances lung cancer growth via the AKT/c‐MYC pathway." (PMID 31397502, 2019). "We previously identified a gene signature associated with sporadic progression to locally invasive adenocarcinoma in a GEMM of lung cancer driven by endogenously expressed KRasG12D combined with modestly overexpressed c-MYC." (PMID 31032816, 2019). "Mechanistic evaluation of one gene, GATAD2B, illuminates its role as a dual activity gene, promoting both pro-tumorigenic and pro-metastatic activities in KRAS-mutant lung cancer through interaction with c-MYC and hyperactivation of the c-MYC pathway." (PMID 30013058, 2018). "It has been reported that CITED2 promotes MYC-mediated transactivation of the E2F3 gene by recruiting p300 to stimulate lung cancer progression." (PMID 30291252, 2018). "Hsa_circRNA_103809 participates in the regulation of lung cancer through the miR-4302/ZNF121/MYC pathway." (PMID 30400981, 2018). "Among the downregulated lncRNAs, MEG3 inhibits lung cancer tumor progression through MYC downregulation." (PMID 29490660, 2018). "At the mechanistic level, the pro-tumorigenic functions of DLX5 have been shown to involve positive regulation of the MYC promoter in human lung cancer cells as well as the IRS2 promoter, an IGFIR adapter protein, in ovarian cancer cell lines." (PMID 30412601, 2018). "In lung cancer, some early studies revealed frequent c-MYC amplification in small cell lung cancer cell lines." (PMID 29494651, 2018). "The endogenous NSD3-s/MYC complexes were also detected in lung cancer H1299 and H1944 cells under physiological conditions by co-immunoprecipitation." (PMID 28205554, 2017). "In summary, our in vitro and in vivo experiments demonstrated that SFN inhibited basal level or cisplatin-stimulated c-MYC expression in lung cancer cells, which are accompanied by enhanced therapeutic efficacy." (PMID 28076844, 2017). "RLIM associates with c-MYC in HEK 293T and human lung cancer H1299 cells, independently of its E3 ligase activity." (PMID 29137325, 2017). "Myelocytomatosis oncogene (MYC) family members, including cellular MYC (c-Myc), neuroblastoma derived MYC (MYCN), and lung carcinoma derived MYC (MYCL), have all been implicated as key oncogenic drivers in a broad range of human cancers." (PMID 28245597, 2017).
lung carcinoma (continued). "As MYC is often overexpressed in tumors including lung cancers and directly binds PD-L1 promoter, these co-treatments are expected to reduce PD-L1 expression." (PMID 28804523, 2017). "To further examine the relationship between CaMKIIγ and two iPSC factors, we downloaded the expression data of CaMKIIγ, OCT4, and MYC in lung cancer from the Oncomine® microarray database for Pearson correlation analysis." (PMID 25965829, 2015). "More importantly, JQ1 also completely abolished the MYC induction by i-CDK9 in HeLa as well as the lung cancer cell line H1792 and the melanoma cell line A2058, whereas the control enantiomer was ineffective in this regard." (PMID 26083714, 2015). "For example, LKB1 is overexpressed partly by degradation of MYC protein to inhibit lung carcinoma cell proliferation." (PMID 26083494, 2015). "The synergistic regulation of these miRNA families and MYC further confirmed their correlation with lung cancer." (PMID 26402252, 2015). "Neratinib and paclitaxel show synergy in the MYC-amplified lung cancer line NCI-H82, i. e. the combination induces a complete response, while the single agents show only a partial effect." (PMID 26018524, 2015). "In colon and lung cancer cell lines, the combination shows general synergistic effects, and higher efficacy in MYC-amplified lung cancer cell lines." (PMID 26018524, 2015). "OmoMyc-mediated MYC inhibition led to a dramatic decrease in tumor-burden in a murine Kras lung cancer model, with only mild side effects, suggesting differential MYC dependency between tumor and normal tissues." (PMID 25495526, 2014). "We identified and confirmed PRKDC (Protein Kinase, DNA-activated, Catalytic polypeptide), a protein kinase with a major role in non-homologous end joining (NHEJ) DNA repair), as a novel synthetic lethal target in MYC-overexpressing lung cancer cells." (PMID 25495526, 2014). "Both miR-143 and miR-145 are able to inhibit cell growth, proliferation and migration of lung cancer cells through the repression of c-MYC, EGFR, NUDT1 and OCT4." (PMID 25593996, 2014). "In conclusion, two main mechanisms, which lead to an overexpression of the miR-17-92 cluster, can be observed in lung cancers: amplification of the miRNA cluster and increased expression of the c-MYC gene." (PMID 25593996, 2014). "In contrast to these studies, in lung carcinomas, BET inhibition rarely down-regulates MYC and the effect of BET inhibitors on proliferation of lung cancer cells is MYC-independent." (PMID 24293458, 2013). "Like miR-17-92, expression of the non-coding RNA H19 has been shown to be induced by MYC in lung carcinomas." (PMID 22852089, 2012). "Among them, NOTCH, WNT and c-MYC are well-established oncogenes in the initiation and progression of lung cancer cells." (PMID 22615765, 2012). "Our results thus far demonstrate that SOX2 regulates the transcriptional network of oncogenes, including WNT1, WNT2, NOTCH1 and c-MYC and promotes the tumorigenesis of human lung cancer cells." (PMID 22615765, 2012). "Expression of this cluster has been shown to be regulated by MYC, an oncogene frequently overexpressed in lung cancer." (PMID 22852089, 2012). "Expression of the MCS in human B cell lymphomas, acute leukemia, lung cancers or Ewing sarcomas has the highest correlation with MYC expression." (PMID 22039435, 2011). "The reduced expression of let-7 in lung cancer directly correlates with upregulation of oncogene ras; introduction of let-7 represses ras and MYC translation by targeting the related mrnas 45,46." (PMID 20179807, 2010).
lung carcinoma (continued). "The presence of a malignancy in the airways was only moderately associated with the rate of copy number abnormalities except for MYC, which was more frequently amplified in preinvasive lesions of patients with lung cancer." (PMID 19547694, 2009). "BACKGROUND: c-MYC and enhancer of zeste homolog 2 (EZH2) are key regulators of cell proliferation and epigenetic reprogramming and have been implicated in the pathogenesis and progression of lung carcinoma." (PMID 41928013, 2026). "Furthermore, the copy number of the oncogene MYC is high in patients with lung cancer brain metastases, and MYC upregulates the expression of pyridoxal phosphate-binding protein SHMT2, which catalyzes the synthesis of serine, glycine, and nucleotides." (PMID 40018041, 2025). "Notably, the role of BRG1 in MYC regulation appears to be context-dependent, promoting MYC expression in leukemia and prostate cancer but repressing it in cardiomyocytes and lung cancer cells." (PMID 40846763, 2025). "USP37 is also upregulated in human lung cancer tissues, and positively correlates with MYC content." (PMID 39858030, 2025). "Interestingly, CDX2 was found to inhibit Wnt signaling in lung cancer cells via suppression of c-MYC, cyclin D1 and survivin expression." (PMID 40002854, 2025). "Therefore, instead of cisplatin, tailored treatments for MYC+ advanced lung cancer can improve clinical outcomes and prevent disease progression." (PMID 40615564, 2025). "In A549 cells, the expression of MRPL9 remains unchanged after c-MYC is knocked down, suggesting that MRPL9 may promote lung cancer metastasis by regulating c-MYC transcription, thereby affecting the expression of migration-related molecules." (PMID 40371222, 2025). "Further research indicates that MRPL9 may promote lung cancer progression by regulating the transcription of c-MYC, especially in lung cancer tissues with high c-MYC expression." (PMID 40371222, 2025). "Downregulation of MYC oncogene expression leads to growth inhibition in lung cancer cell lines." (PMID 40191732, 2025). "Among them, the TF-protein MYC has been demonstrated as a therapeutic target for lung cancer." (PMID 39024368, 2024). "In FGFR1 amplified lung cancers, the levels of MYC gene expression predicted FGFR inhibitor sensitivity, and it has been suggested that high expression levels of MYC may be associated with FGFR inhibitor response." (PMID 39031286, 2024). "SEs might be widespread in almost all cancer MYC regions, whereas studies of SE changes in the MYC region in lung cancer are limited." (PMID 38681203, 2024). "Accordingly, gene set enrichment analysis (GSEA) of the transcriptomic data showed that the Hallmark of MYC targets V1 and V2 are both significantly upregulated in human A549-rtTA-OSKM and mouse L1475luc-rtTA-OSKM lung cancer cell lines, consistent with OSKM expression." (PMID 39587064, 2024). "MYC overexpression is common in many types of cancer, including lung cancer." (PMID 39453005, 2024). "MYC amplification was correlated with chemotherapy resistance in lung cancers." (PMID 36864384, 2023). "Indeed, the MYC gene is amplified in 40% of human cancers, including breast, ovarian, prostate, hepatocellular, colon, and lung cancer." (PMID 37098540, 2023). "As proof of principle, the MYC-inhibitory peptide Omomyc was fused C-terminally to a negatively charged polypeptide, giving rise to efficient membrane penetration and blocking of MYC-dependent transcription in lung cancer cells." (PMID 36969025, 2023). "In addition, KRAS promotes HIF1A-As2 expression via the induction of MYC, suggesting HIF1A-As2 and MYC form a double-regulatory loop to strengthen cell proliferation and tumor metastasis in lung cancer." (PMID 37041291, 2023).